BRCA2 (BRCA2 DNA repair associated)
Diseases named in the same sentence as BRCA2 in open-access papers (continued):
Sharing a sentence is not in itself a finding about the gene and the disease.
breast cancer (continued). "We previously reported that women from high-risk families who tested negative for a BRCA1 or BRCA2 (BRCA1/2) mutation were four times more likely to develop breast cancer compared to women in the general population." (PMID 24667084, 2014). "A cohort of familial breast cancer patients (N = 57), at risk individuals (N = 25) and healthy controls (N = 23) were analyzed using multiplex ligation-dependent probe amplification method to detect BRCA1 and BRCA2 large genomic rearrangements." (PMID 24906410, 2014). "Germline mutations in the BRCA1 and BRCA2 breast cancer susceptibility genes have been associated with up to 15% of TNBC, and TNBC accounts for 70% of breast tumors arising in BRCA1 mutation carriers and 16–23% of breast tumors in BRCA2 carriers." (PMID 24970653, 2014). "The known high risk susceptibility genes for breast cancer, e.g. BRCA1, BRCA2, ATM, and PALB2, are responsible for approximately 20% of the hereditary cases, but several unknown breast cancer–predisposing genetic factors still exist." (PMID 25029565, 2014). "We propose that rare VUS affecting phosphorylation may be a novel and important mechanism for which BRCA1 and BRCA2 functions are disrupted in breast cancer." (PMID 23704879, 2013). "In addition, FANCJ deficiency has been associated with early-onset breast cancer in cells normal for BRCA1 and BRCA2." (PMID 23548139, 2013). "Two of the three BRCA2 VUSs (D1923V and D1923A), were predicted to abolish the CK2 kinase binding at Ser1923 which is a highly evolutionarily conserved residue, also making these variants valid targets for functional analyses in breast cancer." (PMID 23704879, 2013). "This variant, PALB2 c.2993G>A, has previously been identified in studies examining the role of PALB2 in multiple-case breast cancer families that are not known to carry BRCA1 or BRCA2 mutations." (PMID 23448497, 2013). "General classification and within-subtype classification of BRCA1 and BRCA2 breast cancers." (PMID 23704984, 2013). "BRCA2 over-expression, rather than decreased expression, is associated with a poor survival rate and poorer histological findings in breast cancer cohorts." (PMID 24289229, 2013). "Data provided by The Consortium of Investigators of Modifiers of BRCA1/2 (CIMBA) indicated that the FGFR2 locus associated with breast cancer in BRCA2 mutation carriers but not in BRCA1 mutation carriers." (PMID 24171766, 2013). "BRCA1 mutated breast cancers are usually estrogen-receptor negative and have a basal phenotype, while BRCA2 mutated tumours exhibit a broader spectrum of phenotypes." (PMID 24025454, 2013). "Conversely, the absence of PIK3CA mutation in BRCA2 associated MBCs suggests that alternate oncogenic drivers minimally contribute to tumour drive in this group, thus supporting distinct male breast cancer types." (PMID 23971979, 2013). "Overall, the Breast cancer information core (BIC) database (research.nhgri.nih.gov/bic/) has recorded 1,639 and 1,853 distinct mutations, polymorphisms, and variants in the BRCA1 and BRCA2 genes, respectively." (PMID 23354980, 2013). "High DSS1 expression, which potentially stabilizes BRCA2 and maintains cancer cell proliferation, could increase drug resistance under the standard clinical regimens of breast cancer treatment, presumably resulting in decreased disease-free survival." (PMID 24289229, 2013).
breast cancer (continued). "The goal of this study was to determine the prevalence of PALB2 mutations in a population of BRCA1/BRCA2 negative breast cancer patients selected from either a personal or family history of pancreatic cancer." (PMID 23935836, 2013). "Some previous studies presented an association of RAD51 variant allele 135C with an elevated breast cancer risk only in BRCA2 mutation carrier, but not in BRCA1 mutation carriers or non-carriers or unselected populations." (PMID 24040396, 2013). "Li et al16 reported that age at onset of BRCA1-associated breast cancer was significantly earlier as compared with BRCA2-associated and sporadic breast cancers (median age: 36.1 years in BRCA1-associated, 42.7 years in BRCA2-associated, and 47.3 years in sporadic breast cancer)." (PMID 23318652, 2013). "BRCA1 and BRCA2 are the two major genes, but explain only about 20% of inherited breast cancers." (PMID 24139550, 2013). "Even considering the intrinsic limitations of exome resequencing studies, our findings support the hypothesis that the majority of non-BRCA1/BRCA2 breast cancer families might be explained by the action of moderate and/or low penetrance susceptibility alleles." (PMID 23409019, 2013). "Wang et al85 studied 360 samples from Han Chinese and reported that, by interacting with BRCA1 rs4793191 and BRCA2 rs9567623, the ATM polymorphism rs611646 might have a role in breast cancer risk." (PMID 23318652, 2013). "First, the familial breast-ovarian cancer either due to heterozygous germline mutations in BRCA1 (OMIM #604370) or BRCA2 (OMIM #612555), because the index patient and her sister had early-age-onset (≤50 years) breast cancer and the index patient bilateral disease." (PMID 24373500, 2013). "Cao et al64 found that the frequency of disease-related germline mutations in PALB2 was 0.8% (3/360) in BRCA1/BRCA2-negative Chinese women with early-onset or familial breast cancer." (PMID 23318652, 2013). "The youngest affected woman, not known to carry a mutation in BRCA1 or BRCA2, from 747 multiple-case breast cancer families participating in kConFab were selected for PALB2 mutation screening." (PMID 23448497, 2013). "However, nothing is yet known about the involvement of BRCA2 in hypoxic conditions in breast cancer." (PMID 24171172, 2013). "Given the potential benefits versus harms of this testing, the result of our study suggest that PALB2 c.1592delT should be a routine part of the genetic counseling protocol for Finnish high-risk breast cancer cases tested negative for mutations in BRCA1/BRCA2." (PMID 23941127, 2013). "We evaluated whether 191 BRCA1 and 43 BRCA2 VUS from the Breast Cancer Information Core (BIC) database can functionally alter the consensus phosphorylation motifs and abolish kinase recognition and binding to sites known to be phosphorylated in vivo." (PMID 23704879, 2013). "Hemophilia (FVIII, FIX), breast cancer (BRCA2), neurofibromatosis type I (NF1), etc." (PMID 24062987, 2013). "Several studies have indicated that the genetic makeup of BRCA1 and BRCA2 mutation-related breast cancer is different from that of non-BRCA mutation-related breast cancer." (PMID 23409121, 2013). "Nevertheless, we observed up-regulation of p4EBP1 in BRCA2 mutation carriers (68.0%) more frequently than in BRCAX carriers (36.7%), an association not reported in FBC, giving further evidence to the difference in male and female breast cancers." (PMID 23971979, 2013). "However, family history of breast cancer remains a predictive risk factor, after carrier status for BRCA1 and/or BRCA2 mutations has been investigated." (PMID 23326384, 2013).
breast cancer (continued). "In conclusion, BRCA1 and BRCA2 mutations were detected at higher frequency than reported for Korean sporadic breast cancer patients in those patients with no family history of breast or ovarian cancer but with other risk factors of genetic disease." (PMID 22382806, 2012). "The BRCA mutations in male breast cancer without familial breast cancer history are usually undetected and if detected, it is almost always in BRCA2 gene." (PMID 22382806, 2012). "For many years, hereditary ovarian cancer was thought to be mainly, if not entirely, attributable to mutations in the BRCA1/BRCA2 breast cancer susceptibility genes." (PMID 22415235, 2012). "Discovery of the breast cancer-predisposition genes BRCA1 and BRCA2 has enabled us to identify carriers accurately, to target the reduction of risk of breast and ovarian cancers in carriers, and to develop a new generation of targeted therapies (PARP inhibitors)." (PMID 23116406, 2012). "We also found an exon 10 BRCA2 variant (N372H; OMIM_ID # 600185.0133), and an EPCAM variant identified in Chinese population (M143T; rs1126497;) that are associated with increased risk for breast cancer." (PMID 22938532, 2012). "The genomic region of SLX4, comprising all exons and exon-intron boundaries, was sequenced in 94 Spanish familial breast cancer cases that match a criterion indicating the potential presence of a highly-penetrant germline mutation, following exclusion of BRCA1 or BRCA2 mutations." (PMID 22401137, 2012). "Defects in breast cancer susceptibility proteins BRCA1 and BRCA2 (FANCD1) result in HR defects." (PMID 22693661, 2012). "Nonetheless, for women without mutations in BRCA1 or BRCA2, family history remains a strong predictive risk factor for breast cancer." (PMID 22703186, 2012). "Cancers defective in DNA repair, specifically cancers with mutations in the breast cancer associated BRCA1 and BRCA2 genes and triple-negative breast cancer (which shares molecular and pathologic features with BRCA1-related breast cancers) appear to be particularly sensitive to inhibition of PARP-1." (PMID 22619725, 2012). "Taken together, these findings suggest that SNPs rs2380205 at 10p15 and rs614367 at 11q13 do not modify breast cancer risk in either BRCA1 or BRCA2 mutation carriers." (PMID 22348646, 2012). "Likewise, the lifetime risk of developing breast cancer is been reported as high as 80% and 50% for BRCA1 and BRCA2 mutation carriers, respectively; although it varies between different populations and ethnicities." (PMID 22655046, 2012). "Unlike women, BRCA2 germline mutation in men confers a significantly higher lifetime risk of developing breast cancer than BRCA1." (PMID 23146383, 2012). "Overall 43 mutations (18 BRCA1 genes and 25 BRCA2 genes) were identified in high-risk breast cancer patients without a family history of breast or ovarian cancer." (PMID 22382806, 2012). "Overall, mutation of BRCA1 or BRCA2 genes was identified in 65 (8.6%) patients among 758 high-risk breast cancer patients without family history of breast or ovarian cancer." (PMID 22382806, 2012). "Baseline characteristics of breast cancer cases and controls with BRCA1 and BRCA2 mutations." (PMID 22405187, 2012). "We propose that FISH to detect these deletions would be an efficient and cost-effective first screening step to identify potential BRCA2-mutation carriers among breast cancer patients without a family history of breast cancer." (PMID 23284877, 2012).
breast cancer (continued). "The breast cancer susceptibility and Fanconi proteins FANCD1/BRCA2, the partner of BRCA2 (PALB2/FANCN), a helicase associated with BRCA1 (FANCJ/BACH1), and several newly identified components including FAN1, FANCO/RAD51C, and FANCP/SLX4 participate in the pathway to respond to and repair DNA damage." (PMID 22693661, 2012). "PDAC is seen in some breast cancer families with BRCA1 and BRCA2 mutations." (PMID 22873581, 2012). "Canine BRCA2 has also been suggested to have a relationship with mammary tumors." (PMID 22471976, 2012). "Using whole-genome comparative genomic hybridization on microarrays, we screened a cohort of women fulfilling criteria for hereditary breast cancer who did not carry BRCA1/BRCA2 mutations." (PMID 22314128, 2012). "Little is known about the contralateral breast cancer risk in women with familial breast cancer that tested negative for BRCA1 or BRCA2 mutations." (PMID 23216834, 2012). "At the germline level, some studies have shown that the single nucleotide polymorphism (SNP) −135G>C (rs1801320) in the 5′ untranslated region (UTR) of RAD51 modifies breast cancer risk in BRCA2 mutation carriers but not in BRCA1 mutation carriers." (PMID 23300655, 2012). "Despite that lack of knowledge, however, the demand for prophylactic bilateral mastectomy after first breast cancer is increasing not only for mutation carriers but also for women without a BRCA1 or BRCA2 mutation." (PMID 23216834, 2012). "There was a significant reduction in breast cancer risk with breastfeeding among women with a BRCA1 but not a BRCA2 mutation." (PMID 22405187, 2012). "Compared with noncarriers, BRCA1 and BRCA2 mutation carriers have a substantially increased lifetime risk of contralateral breast cancer that is age dependent and can be up to 68%, if the age of the first cancer is <40." (PMID 22838957, 2012). "A mutation analysis of SLX4 in German or Byelorussian familial cases of breast cancer without detected mutations in BRCA1 or BRCA2 has been completed, with globally negative results." (PMID 22401137, 2012). "None of the other polymorphisms was associated with breast cancer risk for BRCA2 mutation carriers under the multiplicative model." (PMID 22348646, 2012). "However, results from a recent population-based study are in line with our risk estimates for contralateral breast cancer in BRCA1 and BRCA2 carriers." (PMID 23216834, 2012). "Up to 50% of women diagnosed with breast cancer, younger than 50 years, and women who have a family cancer history may have mutations in BRCA1 or BRCA2." (PMID 23116406, 2012). "Risk of breast cancer up to 80% is usually observed in BRCA1 and BRCA2 mutation carriers." (PMID 22503188, 2012). "Oophorectomy was associated with a 51% reduction in contralateral breast cancer risk in BRCA2 carriers, but this was not statistically significant (P=0.11)." (PMID 21487411, 2011). "Incidence of BRCA1 or BRCA2 mutations among Slovenian families with only breast cancer history (no ovarian cancer) subdivided according to the number of breast cancer cases in the family." (PMID 21232165, 2011). "For this study, women without breast cancer with at least one first- or second-degree relative diagnosed with breast cancer before age 50 were eligible unless a BRCA1 or BRCA2 mutation had been identified in their family." (PMID 21896163, 2011). "On the other hand, the proportion of detected mutations in BRCA1 and BRCA2 genes fell to 36% when we investigated the subgroup of families with at least two ovarian cancers and no breast cancer in their family history (Subgroup - only O)." (PMID 21232165, 2011).
breast cancer (continued). "The patient had no obvious risk factors for breast cancer such as testicular abnormalities, infertility, obesity, cirrhosis or Klinefelter's syndrome nor was he known to be positive for any BRCA2 mutations." (PMID 21276228, 2011). "Recently the CHEK2 1100delC variant has been found to give a 10-fold risk of male breast cancer independent of BRCA1 or BRCA2." (PMID 21949660, 2011). "The basal-like phenotype is rarely found in BRCA2 breast cancers." (PMID 22295226, 2011). "We find that DNA binding by BRCA2 is critical when a BRCA2 peptide is deficient in binding another breast cancer suppressor, PALB2, but not when the peptide can bind PALB2, suggesting alternative mechanisms of activity." (PMID 22194698, 2011). "However, screening in this age group in the Netherlands is only recommended when women are at high risk for breast cancer, for instance because of an inherited BRCA1 or BRCA2 gene mutation." (PMID 21364575, 2011). "When considering our families with at least two breast cancers and all of them diagnosed after age of 50 and no ovarian cancer (Group D), the mutation detection rate was 5% (only one mutation discovered in BRCA2)." (PMID 21232165, 2011). "In the clinical setting, BRCA1-linked breast cancers are more often of the “triple negative” basal type than are either sporadic or BRCA2-linked breast cancers, for reasons that are not well understood." (PMID 21779182, 2011). "In addition, breast cancers arising in BRCA1 and BRCA2 mutation carriers are heterogenic for LOH, suggesting haploinsufficient effects in pathogenesis." (PMID 21958427, 2011). "One other hospital-based study has evaluated the frequency of BRCA1 (but not BRCA2) mutations among unselected breast cancer cases in Greece." (PMID 22085629, 2011). "The risk of contralateral breast cancer was estimated for patient subgroups defined by age group, gene (BRCA1 vs BRCA2), number of affected first-degree relatives, and by treatment received (surgery, chemotherapy, tamoxifen, radiotherapy, and ovarian ablation)." (PMID 21487411, 2011). "The current results demonstrate that despite lack of an association between a SNP and the overall breast cancer risk for BRCA1 or BRCA2 mutation carriers, residual associations exist with specific disease subtypes." (PMID 22053997, 2011). "Common breast cancer-predisposition alleles may differentially modify breast cancer risk among BRCA1 and BRCA2 mutation carriers." (PMID 22110403, 2011). "The lifetime risk of breast cancer in BRCA1- and BRCA2-mutation carriers is 45–80%." (PMID 22312502, 2011). "The syndromes most strongly associated with both cancers are the BRCA1 or BRCA2 mutation syndromes, but these do not account for most breast cancers that arise in the general population." (PMID 21487409, 2011). "Although previous studies have identified a group of high penetrance susceptibility genes and loci of breast cancer, such as BRCA1, BRCA2, and CHEK2, these genes could only explain a small part of the genetic risk of breast cancer." (PMID 21912531, 2011). "Because of this high risk of breast cancer, women with a mutation in either the BRCA1 or BRCA2 gene are offered breast cancer surveillance, which includes annual clinical breast examination, annual mammography and annual contrast enhanced magnetic resonance imaging (MRI) of the breast." (PMID 21864353, 2011). "Some women with a strong family history of breast cancer inherit BRCA1 or BRCA2 mutations, which have a variable penetrance for breast cancer, between 40 to 66%, suggesting that additional factors contribute to cancer risk among BRCA1 and BRCA2 carriers." (PMID 21708019, 2011).